COL11A1 (collagen type XI alpha 1 chain)
Diseases named in the same sentence as COL11A1 in open-access papers (continued):
Sharing a sentence is not in itself a finding about the gene and the disease.
tumor (continued). "Another study demonstrated that in the TME of ICI-nonresponsive NSCLC patients, SPP1+macrophages and COL11A1+ fibroblasts form highly enriched cellular networks that suppress T cells infiltration into the tumor parenchyma via intercellular interactions." (PMID 41268560, 2025). "Subsequent research demonstrated that COL11A1 stimulates the synthesis of inhibitor of apoptosis proteins (IAPs) such as XIAP, BIRC2, and BIRC3, alters tumor cell metabolism, and upregulates TWIST1 expression, collectively contributing to resistance against cisplatin and paclitaxel therapies." (PMID 41462920, 2025). "COL11A1+ CAFs co-localise with SPP1+ macrophages at tumour borders and their interaction promotes the production of collagen by CAFs, that obstacles the contacts between tumour cells and cytotoxic immune cells, leading to immune exclusion." (PMID 40849356, 2025). "Nonetheless, COL11A1 offers several advantages as a biomarker: it demonstrates high sensitivity and specificity, reflects tumor stromal activity, and provides information independent of traditional epithelial markers such as ER, PR, HER2, or PD-L1." (PMID 41462920, 2025). "In addition, for COL11A1, we performed immunohistochemistry (IHC) on the PDX samples as well as primary tumor samples." (PMID 38702309, 2024). "The results showed a correlation between COL11A1 and ICP genes in the 37 tumor types." (PMID 38649961, 2024). "Additionally, in mouse models of xenograft with ovarian cancer cells, COL11A1 has been shown to stimulate IL-6 production via induction of TGF-β3, modulating the interaction between CAFs and tumor cells and amplifying tumor invasiveness and progression." (PMID 39769286, 2024). "Consistent with the results from non-tumor samples, all the TIMGs that we identified (ENO1, MUC1, COL5A1, COL11A1, IL11, AIM2, JUNB) as well as FABP7, exhibited significantly or moderately elevated expression in multiple TCGA tumors, including GBM, compared to normal tissues." (PMID 39596296, 2024). "Our work provides several advantages over previous studies: the single expression of COL11A1 is able to predict MP infiltration, and it is a nondependent MP presence marker (as smoothelin) because it is tumor stromal marker." (PMID 37760937, 2023). "Our data revealed that CK19, COL11A1, and COL1A2 could be potential tumor biomarkers in plasmatic EVs, since results both at the level of expression as well as specificity and reproducibility are robust and promising." (PMID 36834987, 2023). "Our data suggest that although COL11A1 seems to predict malignancy, consistent with findings published to date, contrasting with other tumor types presented in this work, it does not have a sufficient sensitivity for its use in diagnostic routine." (PMID 37760937, 2023). "The fact that Collagen signatures exhibit strong predictive power may be because these members themselves (COL1A1, COL4A3, COL5A1, COL11A1, COL22A1) have been reported to predict tumor prognosis." (PMID 37476379, 2023). "While there were some IHC markers that are known to be more present in the stromal component (e.g. POSTN, COL11A1), our ovarian TMA was created to maximize the tumor epithelial tissue and the IHC scoring was based on the expression in the tumor epithelial compartment." (PMID 36761962, 2023). "In summary, through comparison between fibroblasts in tumor tissues and normal tissues at single-cell level, we identified that COL11A1+ FBs specifically exist in tumor tissues, but not normal tissues, thus we named them CSFs." (PMID 36744260, 2023). "Although it is established that COL11A1 appears to be mostly expressed by tumor stromal cells, not much is known about the effect of collagen type XI on CAF function." (PMID 36233024, 2022). "Studies on a nude mouse subcutaneous tumor model have also shown that the overexpression of CDX2 and let-7b or the knockdown of COL11A1 could effectively reduce the volume and weight of the tumor." (PMID 35847935, 2022).
tumor (continued). "Also, we discovered that tumour cells of intercalated duct derived SGC and CAFs produce COL11A1 in a mutually exclusive manner." (PMID 34378164, 2022). "Furthermore, the biological functions of LINC00665/miRNAs/COL11A1 were validated in LUAD cells and nude-mouse transplanted tumor model." (PMID 35892083, 2022). "It is not hard to find that COL11A1 is closely related to the infiltration of various tumor immune cells including B Cell, CD8 + T cell, CD4 + T cell, macrophage and neutrophil and dendritic cell." (PMID 36160004, 2022). "Other significant DE genes with high FC(log2), unique to the study were INHBA, COL1A1, COL11A1, COMP, SFRP4 and SPP1, which were clustered in STRING network analysis and correlated with tumour-infiltrating immune cells in TIMER, suggesting a specific interaction pathway." (PMID 34824625, 2021). "Among them, the expression of COL1A1, COL10A1, and COL11A1 were found to be particularly high in tumor tissues compared with normal counterpart; on the contrary, the expression of COL4A4, COL6A5 and COL14A1 was significantly lower in tumor tissues." (PMID 34199373, 2021). "We found that several among the 24 tumor samples contained populations of cells strongly co-expressing COL11A1, THBS2 and INHBA, while none of the normal samples contained such cells." (PMID 34283835, 2021). "Our in silico study reveals that an abundance of COL11A1 mRNA could induce the transcriptional upregulation of THBS2, COL10A1, COL5A2, and COL1A2 genes cooperatively, to promote the neoplasia." (PMID 33597969, 2021). "The PanCancer pathway panel includes multiple collagen genes and our data also showed significantly higher expression of COL11A1, fold change 24.99, p = 0.001, COL5A1, fold change 3.91, p = 2.0x10-8 and COL1A1, fold change 8.40, p = 5.65x10-8 in ILC tumor relative to adjacent normal tissue." (PMID 27078887, 2016). "Tissues analyzed demonstrated significant up-regulation of COL11A1 and COL10A1 in tumor tissue as compared to non-tumor adjacent tissue in the Lebanese, suggesting that both proteins might play a role in local invasion of BC cells." (PMID 27857161, 2016). "Furthermore, more investigative efforts are needed to answer certain unresolved questions by determining the expression of COL11A1 and Akt-PDK1 in clinical tumour specimens from our cohorts." (PMID 26087191, 2015). "Moreover, evidence is still lacking on how COL11A1 modulates the biophysical properties of the tumor extracellular matrix and influences the migration of tumor and immune cells." (PMID 41462920, 2025). "Notably, BBIT20 reduced the collagen content, particularly COL11A1, and α-SMA in PDAC tumours." (PMID 40275348, 2025). "Thus, the normal collagen matrix could be decreased and concurrently replaced by tumor-specific types of collagens (i.e., COL12A1 and COL11A1) in tumor tissues." (PMID 40032993, 2025). "We found that the tumor tissues were hypermethylated compared to the adjacent normal tissues, which could not explain why the COL11A1 gene was highly expressed in LUAD." (PMID 38649961, 2024). "Notably, COL11A1+ FBs only existed in various tumor tissues but not in normal tissues, while other fibroblast clusters existed in both tumor tissues and normal tissues." (PMID 36744260, 2023). "Furthermore, in vivo findings from mouse xenografts indicated the essential role of COL11A1 in tumor progression and CAF activation, and that anti-TGF-β3 therapy could inhibit tumor growth and reverse CAF activation." (PMID 35847935, 2022). "This seeming discrepancy between ISH and MSI results might be traced back to a slow turnover of COL11A1 in AdCy, possibly due to a relative absence of CAFs in these tumours." (PMID 34378164, 2022). "Interestingly, we revealed that while the RNA expression of COL11A1 in AdCy was not particularly high, the protein deposition in the tumours was marked." (PMID 34378164, 2022).
tumor (continued). "We speculate, that this seeming discrepancy might be traced back to a slow turnover of COL11A1 in AdCy, possibly due to a relative absence of CAFs in these tumours." (PMID 34378164, 2022). "Consequently, COL11A1 may complement, rather than replace, traditional biomarkers by providing additional insights into tumor invasiveness, angiogenesis, and therapy resistance." (PMID 41462920, 2025). "No positive correlations were observed for ACTA2, COL11A1, TNC, and PDPN genes in PanCK(-) AOIs at EOCC tumor center or at LOCC tumor invasive margin." (PMID 37964075, 2023). "The analysis of the corresponding tumor and non-tumor samples also revealed upregulation of COMP, matrix proteins such as COL5A1, COL11A1, and FN1, and genes of the Wnt pathway (WNT7B, FZD10, SFRP2), while PLCB1, CAMK2B, PLCB4 and WIF1 are downregulated." (PMID 33227073, 2020). "While an overexpression of COL11A1 has been described for several primaries using bulk expression data, a systematic evaluation of CAFsCOL11A1 with RNA-ISH has not yet been performed in any tumour type." (PMID 34378164, 2022).
connective tissue disorder (7 papers, 2013 to 2025). A disease involving the connective tissue. "COL11A1 is an important component of collagen XI and is considered to play an important role in a variety of connective tissue diseases." (PMID 36160004, 2022). "Spherophakia was not previously reported in STL2, a connective tissue disorder caused by COL11A1 mutations." (PMID 40144770, 2025). "The diagnosis of COL11A1 could only partially explain his phenotype of connective tissue disorder." (PMID 32963807, 2020). "Notably, of the 29 children with nFTS with dysmorphic features resembling connective tissue disorders, 7 had VUSs of genes known to be related to connective tissue (BMP4, MATN3, COL2A1, COL11A1, COL1A1, COL1A2, and COL6A3)." (PMID 40524006, 2025). "Other networks significantly enriched also related to a further network in connective tissue disorders that contained genes including collagens COL10A1, COL11A1 and COL2A1 plus a disintegrin and metalloproteinase with thrombospondin motifs-2 (ADAMTS-2) and fibulin-1 (FBLN1)." (PMID 23971731, 2013).
skeletal dysplasia (4 papers, 2018 to 2024). Any Mendelian diseases that affects growth and development of the skeleton. "A novel missense variant (G to A in exon 45) of COL11A1 resulted in short-limb skeletal dysplasia." (PMID 37108419, 2023). "A novel deleterious heterozygous mutation in COL11A1 was associated with severe skeletal dysplasia." (PMID 37108419, 2023). "A heterozygous deletion in COL11A1 involving exon 48, c.3627_3635del9 was identified in a skeletal dysplasia patient." (PMID 38314968, 2024).
adenocarcinoma (3 papers, 2022 to 2023). A common cancer characterized by the presence of malignant glandular cells. "From 30 adenocarcinomas, 29 presented COL11A1 immunolabeling, while 0 of the 21 noninvasive samples presented positive expression (p < 0.0001)." (PMID 37760937, 2023). "We identified significant overlap in the SqCC and adenocarcinoma risk signatures for matrix components that regulate collagen fibril architecture including COL10A1, COL11A1, and CTHRC1 suggesting that our risk signature represents changes in the organization of fibrillar collagens." (PMID 36404344, 2022). "In a first approach, the COL11A1 expression of typical adenocarcinomas was compared with that of noninfiltrative lesions in order to determine the validity of this marker." (PMID 37760937, 2023).
bone disorder (3 papers, 2016 to 2024). "Among the genes not previously identified through GWAS or not implicated as the index gene in an associated locus, LRP4 and COL11A1 are known to harbor rare mutations that cause monogenic skeletal disease in humans." (PMID 27612175, 2016).
benign tumor (2 papers, 2018 to 2025). "Additionally, benign tumor tissues displayed significantly higher COL11A1 mRNA levels compared to normal tissues (p=0.012)." (PMID 39845732, 2025).
autosomal dominant disease (1 paper, 2021). Autosomal dominant form of disease. "Heterozygous mutations in COL11A1 (OMIM 120280) or COL11A2 (OMIM 120290) have been associated with autosomal dominant disease, although COL11A2‐related disease lacks ophthalmic findings as the gene is not expressed in the vitreous." (PMID 33951325, 2021). "COL11A1‐related autosomal dominant disease was most common in our series, followed by COL2A1‐related autosomal dominant disease." (PMID 33951325, 2021). "COL11A1‐related rather than COL2A1‐related autosomal dominant disease may be more common when undiagnosed children are identified based on ocular exam." (PMID 33951325, 2021). "COL11A1‐related rather than COL2A1‐related autosomal dominant disease may be more common when undiagnosed children are identified based on ocular examination." (PMID 33951325, 2021).
brain disease (1 paper, 2020). "Furthermore, five out of the 12 RG‐specific proteins (COL11A1, RRAS, GLUD1, IFITM3, and MGST1) are involved in human epileptic disorders prompting the hypothesis that modification of the extracellular environment is a common feature in this type of brain disease." (PMID 32378798, 2020).
genetic disorders (1 paper, 2015). "The immobilization-only genes included collagen genes Col2a1, Col10a1, and Col11a1, all previously associated with human genetic disorders with altered joint mobility." (PMID 26006773, 2015).
hematological cancers (1 paper, 2021). "Given the lack of information on the role of COL11A1 in hematological malignancies, it is unknown at this point why COL11A1 functions differently in solid vs. hematological cancers." (PMID 33668097, 2021).
COL11A1 also shares sentences with these, for which no sentence is quoted: cataract (5 papers); Hearing impairment (4); primary angle-closure glaucoma (4); spondyloepiphyseal dysplasia (4); Kniest dysplasia (3); Marfan syndrome (3); rheumatoid arthritis (3); adenoma (2); adrenal cortical carcinoma (2); bladder cancer (2); bladder urothelial carcinoma (2); cecal adenocarcinoma (2); cholangiocarcinoma (2); colon mucinous adenocarcinoma (2); diverticulitis (2); gastric tumors (2); hepatocellular carcinoma (2); infection (2); neurofibroma (2); Nystagmus (2); prostate carcinoma (2); rectal adenocarcinoma (2); Ullrich congenital muscular dystrophy (2); vitreoretinal degeneration (2); Wagner syndrome (2); acinic cell carcinomas (1); acute myeloid leukemia (1); albinism (1); aniridia (1); atherosclerosis (1).
A further 84 diseases each share a sentence with COL11A1 in 1 paper.